ANXA1 (annexin A1)
Diseases named in the same sentence as ANXA1 in open-access papers (continued):
Sharing a sentence is not in itself a finding about the gene and the disease.
Hypertension (6 papers, 2019 to 2026). The presence of chronic increased pressure in the systemic arterial system. "In hypertension, ANXA1 has been implicated in both protective and detrimental roles." (PMID 41208642, 2025). "Recently, a growing number of studies have shown that ANXA1 is closely related to the progression of hypertension." (PMID 41208642, 2025). "At present, studies on the pathological mechanism of ANXA1 and its derived peptides in hypertension are scarce and have only explored pathological changes and molecular phenotypes, while pathways have been overlooked." (PMID 41208642, 2025). "This discrepancy highlights the need for further investigation into the functional heterogeneity of ANXA1 in different hypertension models, particularly through conditional knockout studies and comparisons of gestational versus nonpregnant hypertension." (PMID 41208642, 2025). "The differences in the research progress of pre‐eclampsia and other types of hypertensions suggest that ANXA1 and its derived peptides affect hypertension." (PMID 41208642, 2025). "Further, the role of Annexin A1 in the most prevalent cardiovascular disorder, i.e., systemic hypertension, remains largely unexplored." (PMID 34943928, 2021). "In addition, the novel role of Sirt1, Sirt4 and ANXA1 in hypertension related bone marrow microvascular ageing deserves further study." (PMID 41507140, 2026). "Possible mechanisms of ANXA1 and its derived peptides involved in hypertension." (PMID 41208642, 2025). "Activated (phosphorylated) MYPT1 actively phosphorylates myosin delaying its ability to relax, therefore, inducing prolonged contraction suggesting there could be a link between ANXA1 and the development of hypertension (however this warrants further investigation)." (PMID 30972066, 2019). "We also demonstrated that Ang II-infused TRPM7+/Δkinase mice have severe hypertension and reduced activation of the TRPM7-kinase target proteins annexin-A1 and calpain II44." (PMID 35882956, 2022).
intracerebral hemorrhage (6 papers, 2020 to 2025). A cerebrovascular disorder characterized by bleeding into one or both cerebral hemispheres including the basal ganglia and the cerebral cortex. "Glial cells-mediated neuroinflammation, brain edema and neurological function were attenuated by ANXA1 in mice following intracerebral hemorrhage." (PMID 38790419, 2024). "Administration of ANXA1 following intracerebral hemorrhage injury in mice reduced microglial activation, brain oedema and acute neurological deficiencies, as determined with the sensorimotor Garcia testing paradigm." (PMID 36556373, 2022). "AnxA1 administration was shown to be beneficial in intracerebral hemorrhage, attenuating neuroinflammation via the AnxA1/FPR2/p38 signaling pathway." (PMID 35956787, 2022). "ANXA1 also plays a certain role in patients with spontaneous intracerebral hemorrhage (ICH)." (PMID 41208642, 2025). "Other studies have also shown AnxA1 to exert its effects via the FPR2/ALX/p38 mitogen-activated protein kinase (“MAPK”)/COX-2 pathway in an experimental model of intracerebral haemorrhage, although other MAPKs may also be involved." (PMID 33202930, 2020).
non-alcoholic steatohepatitis (6 papers, 2014 to 2022). "The endogenous ligand for FPR2, annexin A1, has also shown beneficial effects in reducing fibrosis in a mouse model of non-alcoholic steatohepatitis (NASH), while the Annexin A1 derived peptide Ac2-26 reduced collagen deposition in a model of silicosis." (PMID 36793548, 2022). "In mice fed a methionine-choline-deficient diet to induce non-alcoholic steatohepatitis (NASH), hepatic AnxA1 protein levels were nevertheless increased." (PMID 31337068, 2019). "The N-terminal peptide of ANXA1 (Ac2-16) also reduces tissue injury by activating Akt in experimental models of cardiac/renal reperfusion injury and non-alcoholic steatohepatitis." (PMID 30972066, 2019). "Recently, the functional role of macrophage-derived AnxA1 in modulating hepatic inflammation and fibrogenesis during nonalcoholic steatohepatitis (NASH) progression was documented." (PMID 26885535, 2016).
oesophageal cancer (6 papers, 2008 to 2022). "Transposition of ANXA1, which was found in oesophageal cancer, could affect the activities of arachidonic acid metabolism." (PMID 39290334, 2022).
papillary thyroid carcinoma (6 papers, 2013 to 2025). "This validation confirmed that Anxa1 not only plays a role in EndMT but also exerts regulatory control over EMT in papillary thyroid carcinoma." (PMID 39026350, 2024). "Western blotting experiments showed high levels of ANXA1 in papillary thyroid carcinoma and follicular cells while undifferentiated thyroid carcinoma cells had low levels of ANXA1 protein." (PMID 34767591, 2021). "ELISA assays and WB analysis confirmed the increase of LDHB, Moesin, and ANXA1 in pre-surgical FNA of thyroid papillary cancer." (PMID 24023790, 2013). "For instance, ANNEXIN A1 expression was prominently upregulated in papillary thyroid carcinoma (PTC) tumor tissues; furthermore, ANNEXIN A1 regulated EMT and activated the IL-6/JAK2/STAT3 pathway to contribute to PTC malignant behaviors, including PTC cell proliferation, migration and invasion." (PMID 34340715, 2021). "However, the function of ANXA1 in papillary thyroid carcinoma (PTC) has not been reported." (PMID 33531975, 2021).
periodontitis (6 papers, 2011 to 2025). An acute or chronic inflammatory process that affects the tissues that surround and support the teeth. "Other proteins that stand out are neutrophil defensin 1, annexin A1, lysozyme C, resistin, cathepsin G, myeloperoxidase, and azurocidin, which were upregulated between 2.8 and 25.1-fold in periodontitis." (PMID 40384977, 2025). "The influence of annexin A1 (ANXA1)-mediated formylpeptide receptor-2 (FPR2) on periodontal pathology was studied in a rodent model of periodontitis and human periodontal ligament cells." (PMID 41002732, 2025). "A number of these genes were also significantly increased in aging and periodontitis tissues (e.g., ANXA1, HMGB1, S100A8, S100A9, APOE/ß2-GPI, LTF, TSLP)." (PMID 38098978, 2023).
renal fibrosis (6 papers, 2014 to 2026). A final common manifestation of a wide variety of chronic kidney diseases characterized by glomerulosclerosis and tubulointerstitial fibrosis. "Further studies on the roles of ANXA1 in renal fibrosis/sclerosis and in protecting renal tissues from proliferation and inflammation during the evolution of glomerular disorders are warranted." (PMID 24591769, 2014). "Alpha-actinin-1 and Moesin detected after 1 week of UUO may be used as potential biomarkers of tubular injury, whereas Annexin A1, Clusterin and Vimentin may be the candidate markers of renal fibrosis." (PMID 25791774, 2015). "Additionally, ANXA1 was found to be abundantly expressed in renal fibrosis." (PMID 36035163, 2022).
systemic lupus erythematosus (6 papers, 2018 to 2026). An autoimmune multi-organ disease typically associated with vasculopathy and autoantibody production. "High levels of anti-Annexin A1 autoantibodies have been reported in systemic lupus erythematosus (SLE), suggesting this protein is implicated in auto-immunity." (PMID 29751523, 2018). "Consequently, treatment with the ANXA1-mimetic peptide Ac2-26 attenuated macrophage-driven fibrosis, reduced renal lipid accumulation, and ameliorated kidney injury in lupus-prone mice." (PMID 41800263, 2026). "Anti-lipocortin 1 antibodies, homologous of ANXA1, have previously been proposed as a marker of Systemic Lupus Erythematosus (SLE) activity." (PMID 37176025, 2023).
type 1 diabetes (6 papers, 2018 to 2023). "This coincided with a worse diabetic phenotype and severe cardiac and renal dysfunction of streptozotocin (STZ)-induced type 1 diabetes in AnxA1−/− mice." (PMID 33810523, 2021). "We recently demonstrated that the plasma levels of ANXA1 are elevated in patients with type-1 diabetes and multiple sclerosis." (PMID 30972066, 2019). "For instance, exogenous AnxA1 enhanced glucose-stimulated insulin secretion of islet cells, which could be beneficial in islet transplantation strategies as a therapy for type 1 diabetes." (PMID 33810523, 2021). "Thus, the role of Annexin A1, as an endogenous anti-inflammatory mediator, has been examined in cardiorenal complications of type 1 diabetic patients and the streptozotocin (STZ)-induced diabetic mouse model." (PMID 34943928, 2021). "AnxA1 level is elevated in the plasma of individuals with type 1 diabetes independent of renal function impairment." (PMID 36766501, 2023). "This is consistent with our previous finding showing that ANXA1 levels did not correlate with CRP in patients with type-1 diabetes." (PMID 30972066, 2019). "STZ-induced type-1 diabetic mice treated with human recombinant ANXA1 do not develop microvascular complications (diabetic cardiomyopathy and nephropathy) even though they have elevated blood glucose, suggesting a key organ protection effect independent of glucose lowering." (PMID 31114582, 2019).
acute kidney injury (5 papers, 2021 to 2024). Sudden and sustained deterioration of the kidney function characterized by decreased glomerular filtration rate, increased serum creatinine or oliguria. "Thereafter, the impact of an Annexin A1 mimetic peptide (Ac2-26) was explored in rat kidneys subjected to ischemia-reperfusion injury- a model of acute kidney injury (AKI)." (PMID 34943928, 2021). "In another study, serum Annexin A1 was used as an index of success of continuous renal replacement therapy (CRRT) in the setting of pyemic secondary acute kidney injury (AKI)." (PMID 34943928, 2021). "RT-qPCR validated miRNA and mRNAs included IGFBP2 (respiratory system); MMP9 and PDE4B (nervous system); PPARG (cardiovascular system); AKR1B1, ANXA1, and LNC2/NGAL (acute kidney injury); GFER/ALR (liver); and miR-30c-3p (coagulopathy)." (PMID 34573990, 2021). "Also, we did not evaluate whether ANXA1 is effective against acute and chronic itching with other etiologies, such as opioid-induced acute itching, cancer-induced chronic itching and renal failure-induced chronic itching, which is important for translating these findings to clinical patients." (PMID 38790419, 2024).
Anxiety (5 papers, 2021 to 2025). Intense feelings of nervousness, tension, or panic often arise in response to interpersonal stresses. "Upregulation of Anxa1 in some rat models of depression may be explained by its association with anxiety." (PMID 39135796, 2024). "Stress- and anxiety-related inflammatory outcomes (cortisol, annexin-A1, and interleukin-1β) were measured, and the older adults’ perceptions and acceptability of the intervention were gathered through semistructured interviews." (PMID 34574438, 2021).
Autoimmunity (5 papers, 2013 to 2022). The occurrence of an immune reaction against the organism's own cells or tissues. "Recent studies in our laboratory addressed some of the key points relative of Annexin A1 involvement in autoimmunity and, specifically, in SLE and lupus nephrites." (PMID 29751523, 2018). "Between the two, i.e., anti- and pro-inflammatory roles, Annexin A1 also plays a tolarogenic effect within dendritic cells that seems to be considered protective of any autoimmunity activation." (PMID 29751523, 2018). "Exposure to the environment of modified soluble proteins linked with DNA within the extracellular traps of NETs is an excellent model to explain autoimmunity, provided that post-translational modifications, such as in the case of Annexin A1, have occurred." (PMID 29751523, 2018). "Basic research and developments in proteomics technology would be complementary in clarifying the missing point of Annexin A1 as an antigen for autoimmunity." (PMID 29751523, 2018). "The description of pathologic pathways leading to modification of Annexin A1 as a trigger of autoimmunity is a cognitive evolution, but requires more experimental data before becoming a solid concept for explaining autoimmunity in human beings." (PMID 29751523, 2018). "Regulation of innate and adaptive immunity, and more in general of inflammation, is not the topic of this review, but a summary may help the comprehension of Annexin A1 implication in autoimmunity." (PMID 29751523, 2018). "On the other hand, the level of circulating anti-Annexin A1 is strongly correlated with other, and more specific, antibodies that are biomarkers of SLE activity, such as anti-dsDNA suggesting, overall, that autoimmunity, in this case, is not correlated with circulating Annexin A1." (PMID 29751523, 2018).
cervical squamous cell carcinoma (5 papers, 2009 to 2025). A squamous cell carcinoma arising from the cervical epithelium. "The reduced ANXA1 results in the poor prognosis of cervical squamous cell carcinoma." (PMID 41497316, 2025).
dry eye (5 papers, 2015 to 2024). "Of these ALB, ANXA1 and ACTB have previously been seen upregulated in aqueous-deficient or Sjögren’s syndrome related dry eyes." (PMID 38368345, 2024). "Different proteins involved with dry eye dysfunction: ANXA1, ANXA11, CST4, PRDX5, PLAA and S100A6; were validated as biomarkers." (PMID 26287192, 2015). "AnxA1 could be used therapeutically to treat the multiple inflammatory diseases of the ocular surface especially dry eye and ocular allergy as well as to prevent these diseases or to maintain ocular surface homeostasis in health." (PMID 33968020, 2021). "In addition to these extracellular proteins, several intracellular proteins such as Annexin A1 (ANXA1), Annexin A11 (ANXA11), aldehyde hydrogenase 3A1, clusterin, Glutathione-S-transferase P1, have also been shown to be deregulated in tears of dry eye patients." (PMID 30673862, 2019).
injury (5 papers, 2014 to 2023). Damage inflicted on the body as the direct or indirect result of an external force, with or without disruption of structural continuity. "We also found that ANXA1 (Ac2-26) significantly reduced CLP- or LPS-induced pathological kidney injury, improved kidney function, improved the 7-day survival rate, and increased HK-2 cell viability in vivo and in vitro." (PMID 36544058, 2023). "To verify the endogenous reaction of ANXA1 to brain trauma, we measured its expression in the injured hemisphere of CCI mice at different time points." (PMID 33679307, 2021). "We propose that the time interval within 48 h seems optimal for effective strategies to restore BBB integrity in HI-related brain injury during development, of which ANXA1 could have great therapeutic potential." (PMID 36983004, 2023). "The genes that were found to downregulate the most during a fight were ADRB2, HRH1, ANXA1 and PDE4B, with the first two upregulated at baseline for pre-fight samples when compared to control data and the latter two with pre-fight gene expression similar to non-head trauma controls." (PMID 33854105, 2021).
kidney stone (5 papers, 2016 to 2025). "In a more recent study, these investigators explored the role of Annexin A1 in the purported protective effect of estrogen on kidney stone formation given reports of lower risk in female than male." (PMID 34943928, 2021). "A subsequent study further explored the role of Annexin A1 in kidney stone formation in the context of an assessment of the effects of caffeine in this process given reports that caffeinated beverages reduce the risk of kidney stone formation." (PMID 34943928, 2021). "The present study showed that after the oxalate-induced HK-2 cell damage, the expression levels of ANXA1 and CD44 proteins are increased, and the adhesion of CaOx crystals on the cell surface is enhanced, thereby increasing the risk of kidney stone formation." (PMID 38204734, 2024). "Furthermore, caffeine was found to inhibit kidney stone formation by promoting the translocation of annexin A1 to reduce the adhesion of calcium oxalate crystals to renal tubular epithelial cells." (PMID 40151354, 2025). "Authors concluded that caffeine exerts a protective effect against kidney stone formation likely via the translocation of Annexin A1 from the apical membrane of cells into the cytosolic compartment, thereby reducing the crystal-binding capacity of renal tubular epithelial cells." (PMID 34943928, 2021). "The studies focused on the role of Annexin A1 in pathogenesis of nephrolithiasis suggest that downregulation of renal cell membrane Annexin A1 may offer a promising approach." (PMID 34943928, 2021). "It was concluded that these in vitro observations implicate a role for Annexin A1 in nephrolithiasis and kidney dysfunction that may be of relevance to hypercalciuria and kidney stone formation." (PMID 34943928, 2021). "Taken together, our findings showed an in vitro evidence of the protective mechanism of caffeine against kidney stone formation via translocation of annexin A1 from apical surface into cytoplasm to reduce the crystal-binding capacity of renal tubular epithelial cells." (PMID 27924845, 2016).
Laryngeal Tumor (5 papers, 2013 to 2024). "Other studies reported a downregulation of ANXA1 expression in laryngeal tumor tissue, with a concurrent increase in ANXA1 in inflammatory cells situated within the tumor microenvironment." (PMID 38893148, 2024). "The expression of ANXA1 was evaluated in larynx cancer and it was observed that this protein plays a regulatory role in Hep-2 cells, decreasing the growth of these cells." (PMID 27209356, 2016). "In this anti-inflammatory and anti-proliferative study, we have unveiled whether ANXA1 protein could be mediated by receptors for formylated peptides (FPRs) in larynx cancer." (PMID 25490767, 2014). "However, the pharmacological antagonist Boc2 attenuated the antiproliferative activity of ANXA1, suggesting that this receptor plays central roles in the proliferation response in larynx cancer." (PMID 25490767, 2014).
liver fibrosis (5 papers, 2014 to 2025). "The data obtained in the patients with NAFLD/NASH indicate an inverse association between liver expression of AnxA1 and the extension of hepatic fibrosis." (PMID 24668763, 2014). "Fibroblast populations and StromaScore were higher in the high ANXA1 group, suggesting that ANXA1 may also be associated with liver fibrosis in patients with PSC." (PMID 37735492, 2023). "Furthermore, the degree of hepatic fibrosis was enhanced in MCD-fed AnxA1 KO mice, an effect associated with augmented liver production of the profibrotic lectin, galectin-3." (PMID 24668763, 2014). "Increased levels of annexin A1 have been reported in acute idiopathic pulmonary fibrosis and liver fibrosis, while in COPD it promotes lung fibroblast proliferation, migration, and differentiation through ERK1/2 and p38 signalling." (PMID 35207752, 2022). "In line with these clinical data, experimental NASH in AnxA1-KO mice is characterized by increased liver fibrosis, suggesting that AnxA1 can prevent the fibrogenic evolution of NASH." (PMID 24668763, 2014). "Thus, the fibrosis inhibitory effect of ANXA1 makes it a potential for future development of drugs for the treatment of liver fibrosis." (PMID 40717977, 2025). "Stimulation of liver fibrosis in AnxA1-KO animals was unrelated to regulation of hepatic TGF-β1 or of MMP-9 and MMP-13, suggesting that additional factors may contribute to the profibrogenic evolution of NASH." (PMID 24668763, 2014). "Functional studies showed that ANXA1 attenuated CCl4-induced hepatic fibrosis in mice, and the mechanism may be that ANXA1 targets the N-formylpeptide receptor (FPR) to regulate macrophage function and thus inhibits Wnt/β-catenin pathway activation in hepatic stellate cell (HSC)." (PMID 40717977, 2025).